TIGIT (T cell immunoreceptor with Ig and ITIM domains)
Diseases named in the same sentence as TIGIT in open-access papers (continued):
Sharing a sentence is not in itself a finding about the gene and the disease.
colorectal tumor (8 papers, 2018 to 2026). "In pathway three, the Fap2 of F. nucleatum interacts with the TIGIT, an inhibitory receptor that leads to the lymphocyte's apoptosis and creates a tumor immunosuppressive environment that further progresses the colorectal tumor." (PMID 34659955, 2021). "We found that the expression levels of PD-1, CTLA-4, TIM-3, TIGIT, PD-L1, and galectin-9 were significantly higher in colorectal tumor tissues, compared with colon normal tissues." (PMID 30081950, 2018). "In this study, we found that expression of ICs including PD-1, CTLA-4, TIM-3, TIGIT, and IC ligands including PD-L1 and galectin-9 was significantly higher in colorectal tumor tissues compared with normal tissues." (PMID 30081950, 2018). "Moreover, TIGIT−/− was shown to significantly inhibit tumorigenicity in both CT26 tumor-bearing BALB/c mice and MC38 tumor-bearing C57BL/6 mice, whereas an anti-TIGIT mAb significantly inhibited tumor growth in both of these colorectal tumor models." (PMID 31681269, 2019). "Interestingly, we found that ICs including PD-1, CTLA-4, TIM-3 and TIGIT, and IC ligands including PD-L1 and galactin-9 were significantly upregulated in colorectal tumor tissues (TT), compared with colon normal tissues (NT)." (PMID 30081950, 2018). "Anti-TIGIT antibody and recombinant mouse PVR protein were used to treat the colorectal tumor CT26 bearing mice." (PMID 30555485, 2018).
cutaneous melanoma (8 papers, 2020 to 2024). A primary melanoma arising from atypical melanocytes in the skin. "Expression of TIM-3 and, to a lesser extent TIGIT, and potentially ligands related to these, could indicate means of immune evasion in UM that are different from cutaneous melanoma." (PMID 32313009, 2020). "Similarly, TIGIT expression was shown to be epigenetically regulated via DNA methylation in skin melanoma, suggesting that TIGIT DNA methylation and expression may serve as predictive biomarkers in the context of immunotherapies." (PMID 39064019, 2024). "As in cutaneous melanoma, the anti-MAA clonotypes formed frequent inhibitory interactions with tumor cells via PVR – TIGIT/CD96 and with immune cells via Galectin 9 – TIM3." (PMID 36220826, 2022). "Farshidfar and colleagues identified that acral melanomas have a lower overall immune cell infiltrate as compared to traditional cutaneous melanoma, but of these infiltrates, PD-1, LAG-3, CTLA-4, VISTA, TIGIT, and ADORA2 were highly expressed, introducing new possible therapeutic targets." (PMID 39001457, 2024). "Furthermore, CD274 (PD-L1) expression correlated significantly with the rest immune checkpoints (apart from VTCN1) in skin melanoma compared to normal skin (not exposed to the sun), especially with PD-L2, ILT2, HAVCR2 and TIGIT." (PMID 36389735, 2022).
esophageal cancer (8 papers, 2016 to 2025). A primary or metastatic malignant neoplasm involving the esophagus. "This concept has been supported by clinical findings in esophageal cancer, where dual inhibition of TIGIT and PD - 1 achieved improved objective response rate (ORR, 27.8%) and disease control rate (DCR, 50%) in immunotherapy-naïve patients (33.3% of whom had adenocarcinoma)." (PMID 40977703, 2025). "In esophageal cancer, AIF-1 has emerged as a novel prognostic gene related to the tumor microenvironment, immune infiltration, and TIGIT expression." (PMID 37014322, 2023). "We also detected several other co-inhibitory molecules (PD-1, TIGIT, and LAG-3) on the surface of NK cells in 5 esophageal cancer patients." (PMID 31109341, 2019). "We examined the correlations between PD-1 and TIM-3 or TIGIT expression in CD4+ and CD8+ T cells in PBMC (n = 35), AEM (n = 25) and tumor tissues (n = 25) from esophageal cancer patients." (PMID 27577071, 2016). "Above results showed that PD-1, TIM-3, TIGIT and BTLA expressions were dysregulated on a fraction of peripheral blood T cells of esophageal cancer patients." (PMID 27577071, 2016). "Recent advances in cancer immunotherapy extend beyond PD-1/PD-L1 blockade to include novel checkpoint targets (e.g., LAG-3, TIGIT), engineered cellular therapies, and strategies to remodel the tumor microenvironment (TME)—strategies increasingly relevant to esophageal cancer." (PMID 40842543, 2025). "In two cohorts of esophageal cancer, the expression of PD-1, PD-L1, TIGIT and TIM-3 was downregulated in CD3+CD4+ T and CD3+CD8+ T cells in patients well responding to 2 and 4 Gy RT while PD-1, PD-L1 and TIGIT were elevated in those poorly." (PMID 37833255, 2023). "We next assessed the expressions of PD-1, TIM-3, TIGIT and BTLA on CD4+ and CD8+ T cells isolated from esophageal cancer tissues, adjacent esophageal mucosa (AEM), and peripheral blood mononuclear cell (PBMC) from esophageal cancer patients." (PMID 27577071, 2016). "However, results are conflicting, and several studies have failed to prove a prognostic role for TIGIT expression, specifically in esophageal cancer, medullary thyroid carcinoma, NSCLC, and SCLC." (PMID 37109579, 2023).
lung squamous cell carcinoma (8 papers, 2022 to 2025). "In lung squamous cell carcinoma, YTHDF1 is significantly negatively correlated with PD-L1, PD-1, PD-L2, CTLA-4, TIGIT, VISTA, and TIM3." (PMID 36479088, 2022).
myelodysplastic syndrome (8 papers, 2020 to 2025). A clonal hematopoietic disorder characterized by dysplasia and ineffective hematopoiesis in one or more of the hematopoietic cell lines. "On the other hand, reduction in the number and function, high expression of T cell immunoglobulin and ITIM domain (TIGIT) of NK cells has been implicated in myelodysplastic syndrome (MDS), a condition that can progress to AML." (PMID 40726987, 2025). "High-risk patients with myelodysplastic syndrome (MDS) express higher levels of TIGIT and PD-1 in peripheral blood T and NK cells than low-risk patients." (PMID 33670993, 2021). "However, the therapeutic potential of blocking TIGIT in myelodysplastic syndrome (MDS) remains unclear and further research is required to reveal their role." (PMID 32903786, 2020). "Increased expression of TIGIT has previously been described for several cancer entities including AML and myelodysplastic syndrome." (PMID 34884723, 2021). "Also, inhibiting TIGIT/CD155 restored NK cell function in myelodysplastic syndromes (MDS)." (PMID 38229100, 2024).
neuroblastoma (8 papers, 2023 to 2025). Neuroblastoma (NB) is the most common solid, extracranial childhood tumor. "TIGIT blockade in vitro resulted in significantly enhanced killing of neuroblastoma tumoroids by immune cells, when combined with PD-L1 blockade." (PMID 38181797, 2024). "TIGIT (+PD-L1) blockade induces numerous complete responses (CR) in vivo, even against chemotherapy-resistant neuroblastoma, highlighting TIGIT blockade as promising immunotherapy for neuroblastoma." (PMID 38181797, 2024). "We confirmed significantly increased CD96 expression, and a trend of increased TIGIT expression in neuroblastoma-infiltrating NK cells by flow cytometry." (PMID 38181797, 2024). "Combined blockade of TIGIT and PD-L1 significantly reduces neuroblastoma growth, with complete responses (CR) in vivo." (PMID 38181797, 2024). "To investigate the therapeutic potential of TIGIT blockade in neuroblastoma, we explored its functional role in tumor killing." (PMID 38181797, 2024). "Taken together, TIGIT blockade may add a survival benefit in the context of chemotherapy resistance in patients with neuroblastoma, when combined with the currently favored relapse treatment protocol." (PMID 38181797, 2024). "We investigated chemotherapy effects on the expression of PD-L1 (PD-1), CD86 (CTLA-4), CD155 (TIGIT), and Gal-9 (TIM-3) immune checkpoint ligands by neuroblastoma cells." (PMID 36765861, 2023). "Moreover, neuroblastoma-infiltrating T cells, particularly DUSP4+ CD4 T cells and CD8 T cells, displayed active downstream TIGIT and PD-1 signaling." (PMID 38181797, 2024).
breast tumor (7 papers, 2018 to 2025). "NECTIN2 and NECTIN4 secreted by BCSC interacted with CD96 and TIGIT on immune cells, causing T-cell inhibition and immune escape at primary breast tumors." (PMID 34611125, 2021). "In this study, we show that CD8+ TILs in human breast tumors are predominantly of effector memory phenotype, express checkpoint molecules PD-1, TIGIT, and 2B4, and are enriched for PD-1+ Eomes+ T-bet− cells." (PMID 30327458, 2018). "This study critically advances our knowledge of the epigenetic modifications behind the transcriptional upregulation of PD-1, CTLA-4, TIM-3, LAG-3, TIGIT, and PD-L1 in breast tumor tissues." (PMID 29983831, 2018). "We then used immunohistochemistry to assess TIGIT expressions in breast tumor tissues." (PMID 35770416, 2023). "Studies indicate that TIGIT, PD-L1, and TIM-3 are significantly upregulated in the peripheral blood of patients with breast tumors." (PMID 35770416, 2023). "In our study, we checked the expression of immune checkpoints/ligand including PD-1, CTLA-4, TIGIT, TIM-3, LAG-3, and PD-L1 and found that PD-1, CTLA-4, TIM-3, and LAG-3 were upregulated in breast tumor tissues, compared with normal tissues." (PMID 29983831, 2018).
chronic lymphocytic leukemia (7 papers, 2019 to 2025). "TIGIT expression was also found to be significantly increased in CD4+ T cells from chronic lymphocytic leukemia patients, and an increased number of TIGIT+ CD4+ T cells was found in patients with advanced disease stage." (PMID 31681269, 2019). "Likewise, CD4+ TIGIT+ T cells were increased in chronic lymphocytic leukemia (CLL) patients, which was also correlated with unmutated immunoglobulin heavy chain variable region (IgHv) and advanced stage." (PMID 36605439, 2022). "A TIGIT role in T cell exhaustion was also reported in chronic lymphocytic leukemia (CLL)." (PMID 35656508, 2022). "Interestingly, a distinct role for TIGIT has been suggested in both solid and hematological tumors, as demonstrated by its high expression on CD4+ but not CD8+ T cells in chronic lymphocytic leukemia (CLL)." (PMID 39684559, 2024).
esophageal squamous cell carcinoma (7 papers, 2021 to 2025). Esophageal squamous cell carcinoma (ESCC) is a type of esophageal carcinoma (EC) that can affect any part of the esophagus, but is usually located in the upper or middle third. "TIGIT was upregulated in immune cells following RT in both esophageal squamous cell carcinoma patients and mouse models." (PMID 35794399, 2023). "Co-expression of immune checkpoints, such as PD-L1 and TIM-3/TIGIT, has been correlated with poor overall survival in several cancer types, including esophageal squamous cell carcinoma, underscoring the potential of combination therapies targeting these checkpoints to enhance clinical outcomes." (PMID 40458414, 2025).
influenza (7 papers, 2020 to 2025). An acute viral infection of the respiratory tract, occurring in isolated cases, in epidemics, or in pandemics; it is caused by serologically different strains of viruses (influenzaviruses) designated A, B, and C, has a 3-day incubation period, and usually lasts for 3 to 10 days. "Lastly, we investigated whether the high proportion of activated TIGIT+Helios+ cells at the onset of influenza correlated with self-reported influenza-A-associated symptom duration." (PMID 35651622, 2022). "We also included TIGIT+KLRG1+ CD8+ T memory cells sorted from both acute (influenza (FLU) and chronic (CMV) viral-specific T cells identified using pentamer staining." (PMID 38650930, 2024). "TIGIT+Helios+ T cells are highly activated during the acute phase of influenza infection and this activation showed a strong positive relationship with the duration of flu-associated coughing." (PMID 35651622, 2022). "Moreover, we show that TIGIT+Helios+ T cells are highly activated during influenza and correlate with prolonged coughing." (PMID 35651622, 2022). "The observed alteration of TIGIT+ pTfh, AM B cell, and CD11b+ monocyte population frequencies in IL-21–treated animals represents immune correlates of influenza vaccine responses in SIV+ aged RM and may be indirectly or directly modulated by IL-21 immunotherapy." (PMID 34491910, 2021). "TIGIT and Blimp-1 expression also correlated at the protein level, where Blimp-1 was exclusively expressed in TIGIT+ Treg cells and induced only after infection with LCMV or influenza." (PMID 41094201, 2025). "While percentages of TIGIT+ Treg specific for C. albicans and K. pneumoniae were comparable to those specific for S. aureus, those specific for SARS-CoV-2 spike protein or for an inactivated tetravalent influenza vaccine were significantly lower." (PMID 39981298, 2024). "The number of influenza-A specific TIGIT+Helios+ was relatively low in all 4 donors, suggesting that the majority of activated TIGIT+Helios+ cells are not influenza specific." (PMID 35651622, 2022). "In agreement with these, compared to circulating Treg cells, we found that lung tissue resident Treg cells express higher levels of PD-1, TIGIT and GITR, even at the naïve state, while ICOS and LAG-3 are significantly upregulated following acute influenza infection." (PMID 36159872, 2022). "In addition to such regulatory role of TIGIT in LCMV and influenza, some recent studies have shown that TIGIT and Helios are expressed by subsets of CD8+ regulatory T cells and contribute to their suppressive function." (PMID 35651622, 2022). "Here the authors show that TIGIT also limits immune pathology during LCMV or influenza infections in mice by driving IL-10 expression without negatively affecting the viral load." (PMID 32152316, 2020). "Here we report that TIGIT modulation effectively alters the phenotype and cytokine profile of T cells during influenza and chronic LCMV infection, but does not affect virus control in vivo." (PMID 32152316, 2020).
liver fibrosis (7 papers, 2023 to 2026). "TIGIT deficiency can inhibit parasite (Schistosoma japonicum) infection-induced liver fibrosis by increasing NK cell-mediated apoptosis HSCs." (PMID 37239062, 2023). "In addition to the suppressive effect of TIGIT on CD226-mediated activation of NK cells, TIGIT deficiency can suppress parasite (Schistosoma japonicum) infection-induced liver fibrosis." (PMID 37239062, 2023). "Previously, we reported that knocking down TIGIT enhanced NK cell function and attenuated liver fibrosis in schistosomiasis." (PMID 40244063, 2025). "In the present study, we identified that TIGIT inhibited NK cell function and reduced the degree of schistosomiasis-induced liver fibrosis." (PMID 36930687, 2023). "In sum, results show that PD-1 and TIGIT are associated with impaired NK cell functionality in persons coinfected with HIV/HCV, but only PD-1 is differentially expressed throughout the liver fibrosis stages." (PMID 38107019, 2023). "Anti-TIGIT therapies are being studied for cancer treatment, so it is plausible to consider them as a therapy to improve NK functionality and secondary liver fibrosis." (PMID 38107019, 2023). "While similar frequencies of CD107a+ NK cells were registered by Tim3 expression, in cases of mild and advanced liver fibrosis, the proportion of degranulating NK cells was significantly reduced when TIGIT was expressed." (PMID 38107019, 2023). "In a mouse model of Schistosoma japonicum infection, TIGIT knockout also reduced liver fibrosis." (PMID 40526725, 2025). "However, with the progression of S. japonicum infection, TIGIT expression increased significantly, indicating that the TIGIT receptor plays a crucial role in inhibiting NK function in liver fibrosis induced by S. japonicum infection." (PMID 36930687, 2023). "Here, we aimed to study PD-1, TIGIT, and Tim3 as potential exhaustion markers in NK cells from persons coinfected with HIV/HCV with mild and advanced liver fibrosis." (PMID 38107019, 2023). "In addition, analysis of peripheral NK cells revealed a progressive increase in the expression of NK exhaustion markers of PD-1, TIGIT, and LAG-3 with advancing stages of liver fibrosis." (PMID 40643462, 2025). "Finally, we studied the distribution of NK cell populations defined by the expression of PD-1, Tim3, and TIGIT in individuals coinfected with HIV/HCV with mild and advanced liver fibrosis." (PMID 38107019, 2023). "Nevertheless, TIGIT was not differentially expressed on NK cells from individuals with different degrees of liver fibrosis." (PMID 38107019, 2023).
sarcoidosis (7 papers, 2019 to 2025). Sarcoidosis is a multisystemic disorder of unknown cause characterized by the formation of immune granulomas in involved organs. "Surprisingly, lymphoid cells in non–sarcoidosis-affected skin specifically induced immune checkpoint genes, including TIGIT, LAG3, and PDCD1." (PMID 39225100, 2024). "TIGIT expression was higher in CD4-positive cells of sarcoidosis patients than in the controls, confirming our previous results." (PMID 36613701, 2022). "CD4+PD1+ and CD4+TIGIT+ cell subsets were higher in sarcoidosis than in HC (p = 0.0250 and p = 0.0014, respectively) and higher in MPA than in HC (p = 0.0117 and p = 0.0113, respectively)." (PMID 36613701, 2022). "The present study analyzed, for the first time, the CTLA4, PD1 and TIGIT expression on T and NK cell subsets in the peripheral blood of sarcoidosis, MPA and GPA patients." (PMID 36613701, 2022). "In contrast to the largely balanced TIGIT : PD-1 expression ratio in thyroiditis, sarcoidosis was characterized by relative overexpression of TIGIT." (PMID 30733837, 2019). "We observed lower percentages of CD4+- and CD8+-TIGIT+ in sarcoidosis patients than in our fibrotic groups, IPF and PCPF, suggesting that the latter disorders may express a higher degree of exhaustion of T cells." (PMID 38540243, 2024). "In line with a more severely exhausted phenotype, our data show a more impaired immune system in IPF than in sarcoidosis patients, as demonstrated by the highest CD4-, CD8-, and CD56-PD-1+ TIGIT+ cell percentages." (PMID 38540243, 2024). "Among T cells, we found increased levels of IL-2R+ TIGIT+ LAG3+ CD4+ T cells in IPF, increased levels of CXCR3+ CD226+ CD4+ T cells in sarcoidosis, and increased levels of PD1+ TIGIT+ CD57+ CD8+ T cells in CTD-ILDs." (PMID 36949950, 2023). "Increased expression of CTLA4 and TIGIT, along with decreased expression of PD1, was reported on the T and NK cells of sarcoidosis patients compared with AAV patients and the HC group." (PMID 36613701, 2022). "Our study described, for the first time, increased PD1, TIGIT and CTLA4 expression on CD4 cells of sarcoidosis patients." (PMID 36613701, 2022). "The PCA plot distinguished the disease clusters: MPA, GPA, sarcoidosis and HC showed that they were separated on the basis of CD4+CTLA4+, CD4+PD1+, CD4+TIGIT+, CD56, CD56+CTLA4+, CD56+TIGIT+, CD8, CD8+CTLA4+ and CD8+PD1+." (PMID 36613701, 2022). "In sarcoidosis, fluorescence measurement further revealed compartment-specific differences of TIGIT, but not of PD-1 expression; TIGIT levels were significantly higher in T cells (including CD4+, CD8+, and FOXP3+) in the intergranulomatous area as compared to the granulomas (p < 0.05)." (PMID 30733837, 2019).